AR (androgen receptor)
Diseases named in the same sentence as AR in open-access papers (continued):
Sharing a sentence is not in itself a finding about the gene and the disease.
liver cancer (continued). "The results indicate that 10–90 μM fisetin did not reduce the cell proliferation of Clone 9, however it significantly attenuated the proliferation of HA22T parental cells, and especially AR and SR liver cancer cells in a dose-dependent manner." (PMID 31261976, 2019). "The androgen receptor (AR) regulates tumorigenesis in many human cancers, including prostate, breast, kidney, lung, bladder, and liver cancer." (PMID 31116991, 2019). "Androgen up-regulates Nanog expression, and AR binds directly to AREs in the promoter region of Nanog in liver cancer cells." (PMID 29716628, 2018). "The disparities of liver cancer and visceral fat deposition potentially originate from high androgen receptor (AR) density." (PMID 27703473, 2016). "The study also confirmed that the positive rate of AR expression in primary liver cancer cells is significantly higher than that in adjacent cells (P<0.05)." (PMID 25667651, 2015). "With pbMOO approach, a new pathway “TGFβ1- TGFβR1- AR-OCIAD2” in liver cancer mesenchymal stem cell was predicted, which will differentiate into Tumor-Associated-Fibroblasts (TAFs), one of the major components of tumor stroma." (PMID 24949437, 2014). "Although the underlying mechanisms governing the FOXA1-AR correlation in tumor progression are not fully understood, a pathway analysis showed that 187 FOXA1/AR dual target genes were involved in the cellular growth/proliferation pathway in liver cancer." (PMID 24512546, 2014). "Pathway analysis in liver cancer shows that FOXA1/AR dual target genes are most involved in the cellular growth/proliferation pathway." (PMID 24512546, 2014). "Disease-related types include epidermal growth factor receptor (EGFR) for cancer, Ataxia telangiectasia mutated (ATM) for Ataxia telangiectasia and Androgen receptor (AR) for liver cancer conserved in both mammals and fish." (PMID 25520927, 2014). "Moreover, the responsiveness of the liver cancer cells that we tested also closely reflects their AR expression status." (PMID 40940976, 2025). "Indeed, various studies demonstrated that androgen/AR-FL exacerbated cell proliferation and liver cancer development under experimental conditions." (PMID 36746917, 2023). "Hence, we further investigated the gene expression profiles and enriched biological processes in the male hep-c-MYC/AR-FL liver cancer." (PMID 36746917, 2023). "There is an increasing amount of evidence linking the AR to liver cancer." (PMID 35163477, 2022). "Previous network pharmacological studies had also found that AR and MYC could play a key role in the process of viral hepatitis, liver cirrhosis, and liver cancer and inhibit the expression of AR, JUN, and MYC, which reduce the occurrence of liver cancer." (PMID 35330838, 2022). "AR-dependent gender differences in liver cancers have also been studied in mice and zebrafish." (PMID 34943942, 2021). "In liver cancer, macrophages might exert effects by secreting miR-92a-2-5p in exosomes to decrease liver cancer cell AR expression, which then leads to increased liver cancer cell invasion." (PMID 33168028, 2020). "AR signal transduction is involved in many aspects of the pathogenesis of liver cancer." (PMID 32963562, 2020). "Androgen/androgen receptor (AR) signaling has an important role in initiation and progression of many hormone-related cancers including prostate, bladder, kidney, lung, breast, and liver cancer." (PMID 33082888, 2020). "Moreover, this regulation seems to only exist in HCC whereas it is much less pronounced in normal liver cells and other tissue type, reflecting potentially a specific role of AR/ADAR1-regulated expression of circRNA in liver cancer progression." (PMID 29144509, 2017). "Moreover, the interaction between androgen and androgen receptor was firstly described as a facilitating factor for PEG10 expression in hepatic cancer, and then confirmed in gastric cancer." (PMID 28193232, 2017).
liver cancer (continued). "Therefore, many researchers have started studying about the role that AR plays not only in the early phase of cancer development but also in the progression, metastasis, and recurrence of liver cancer." (PMID 27340775, 2016). "Additionally, in liver cancer cells treated with Metformin, the protein expression level of AR was downregulated, suggesting that the AR protein might be a new target of Metformin." (PMID 40583627, 2025). "Additionally, AR mRNA levels decrease in liver cancer tissue relative to adjacent normal controls." (PMID 36430245, 2022). "Thus, we find a new pathway between AR and liver cancer progression, and may provide new strategies to better suppress liver cancer progression." (PMID 34745992, 2021). "Moreover, macrophage-derived miR-92a-2-5p-containing exosomes could increase the invasiveness of liver cancer cells, through the modulation of AR/PHLPP/p-AKT/β-catenin axis." (PMID 34831421, 2021). "Finally, miR-367-3p could increase the effectiveness of sorafenib in the suppression of liver cancer metastasis via the modulation of AR signals." (PMID 34831421, 2021). "In conclusion, our study found that AR could suppress liver cancer cells invasion and proliferation capacities via miR-122-5p/RABL6 signaling, and miR-122-5p could suppress the expression of RABL6 to influence liver cancer cells progression by directly targeting the 3’UTR of RABL6-mRNA." (PMID 34745992, 2021). "Thus, we find a new pathway between AR and liver cancer progression, and targeting this new pathway may provide us with better therapies for HCC." (PMID 34745992, 2021). "This possibility could be addressed by testing females lacking both estrogen receptor α and the androgen receptor for their susceptibility to liver cancer." (PMID 34068249, 2021). "Here, our study showed that AR could suppress liver cancer cells invasion and proliferation capacities via miR-122-5p/RABL6 signaling, and miR-122-5p could suppress the expression of RABL6 to influence liver cancer cells progression by directly targeting the 3’UTR of RABL6-mRNA." (PMID 34745992, 2021). "AR may be a marker for the response of patients with liver cancer to sorafenib." (PMID 32963562, 2020). "In addition, ASC-J9® could suppress AR-mediated tumor growth in several cancers, including liver cancer and BCa." (PMID 31234917, 2019). "In this study, we propose repurposing the anthelmintic drug niclosamide for use in liver cancer due to its desirable anti-HCC properties and ability to lower AR/AR-SV protein levels." (PMID 40805231, 2025). "Robust positive correlations are evident with key hormonal markers such as AR (ρ = 0.668), ESR1 (ρ = 0.547), and THRB (ρ = 0.424), underscoring the intricate involvement of SELENOP in hormonal pathways within the realm of liver cancer." (PMID 39001444, 2024). "It was further shown that STAT3 can cooperate with androgen receptor (AR) to induce expression of cell cycle‐related kinase (CCRK), and thus, enhance the tumorigenicity of liver cancer." (PMID 34766135, 2021). "Previous reports demonstrate that AR promotes gender disparities in cancer 10, and TLR4 plays an important role in promoting liver cancer." (PMID 31956356, 2020). "Although AR-AKT signaling is common in prostate and liver cancers, the cellular outcome differs between the two diseases." (PMID 27340775, 2016). "In this study, we employed a combination of in silico molecular docking and in vitro cell validation experiments to identify three ferroptosis suppressor genes, AR, HIF1A, and CA9, as promising components of a survival prognosis model during the metformin‐induced ferroptosis process in liver cancer." (PMID 40583627, 2025). "In one report, AR expression levels were positively correlated with the recurrence rate of HCC and negatively correlated with the survival rate, indicating AR as a promoter in liver cancer." (PMID 41228208, 2025).
liver cancer (continued). "The macroscopic analyses showed that AR-FL co-expression moderately exacerbated the c-MYC-driven liver cancer in male mice, but not in female mice." (PMID 36746917, 2023). "Despite the relevant role played by the androgen/AR axis in the pathogenesis of HCC, probably only a small proportion of liver cancers (about one third) overexpress AR and could be responsive to AR inhibition." (PMID 37508414, 2023). "In addition, CCRK is also involved in the AR and Wnt/β-catenin/TCF signalling pathway cascades in human liver malignant neoplasms." (PMID 36276294, 2022). "Studies have shown that AR degradation enhancer, ASC-J9, may have a certain effect on the treatment of liver cancer, but it still remains controversial." (PMID 34745992, 2021). "By using the TCGA liver cancer database and Spearman’s test, we found a negative correlation between AR and PD-L1 expression level (Correlation coefficient = −0.20, P= 0.014)." (PMID 32579541, 2020). "Our present results suggest that GNMT is a direct AR target gene in PCa, we suspect that AR signalling may also play an important role in GNMT regulation in liver cancer." (PMID 23883094, 2013). "Indeed, AR-SV expression in liver cancer could favor HCC progression by regulating the epithelial-to-mesenchymal transition pathway and determining resistance to traditional AR antagonists." (PMID 37508414, 2023). "However, studies on AR expression in non-prostatic malignancies uncovered that AR-SVs are expressed in glioblastoma, breast, salivary, bladder, kidney, and liver cancers, where they have diverse roles in tumorigenesis." (PMID 37626712, 2023). "AR-FL co-expression showed moderate increases in the expression of these pro-oncogenic genes and could contribute similarly to the exacerbation of the c-MYC-driven liver cancer development in males, but at a much-reduced level." (PMID 36746917, 2023). "In addition, GEPIA online analysis showed that ESR1, AR, CCNB1, CDK1, AKR1C3 and CCNA2 might become potential target genes for the survival and prognosis of PADP for the treatment of liver cancer." (PMID 35463358, 2022). "Besides, exosome transportation of miR-92a-2-5p from macrophages to liver cancer cells could suppress AR expression by directly targeting AR 3′UTR and enhance the invasion capacity of liver cancer cells." (PMID 33869227, 2021). "It was noted that the expression of matrix metalloproteinase 9 (MMP9), an important marker of migration, adhesion, invasion and metastasis of liver cancer, was higher in HCC tumors in mice lacking specific AR in the liver (L-AR−/y) compared to WT-animals." (PMID 32290381, 2020).
glioblastoma (66 papers, 2015 to 2026). The most malignant astrocytic tumor (WHO grade IV). "In contrast, androgen receptor signaling in males has been implicated in glioblastoma progression, with evidence suggesting that androgen receptor activation promotes tumorigenesis, potentially by inhibiting tumor-suppressive TGF-β signaling." (PMID 41346390, 2025). "A special focus on the androgen receptor (AR) and its pathogenic role in glioblastoma has been provided in the last decade." (PMID 38233838, 2024). "Regarding the role of the AR in glioblastoma, its activation has been associated with increased proliferation of glioblastoma cells and increases in their migration and invasiveness capacity." (PMID 38233838, 2024). "A higher AR expression in glioblastoma biopsies than in the normal brain has been reported, and AR expression has been associated with the histological grade of glial tumors; a high AR expression is found whenever the tumoral grade increases." (PMID 38233838, 2024). "In contrast, suppression of AR activity by enzalutamide pretreatment caused a 68% decrease in testosterone-induced colony formation in human U87 MG glioblastoma cells." (PMID 36013056, 2022). "Research suggests that this difference may be linked to the modulation of glioblastoma pathogenesis via the androgen receptor (AR) signaling pathway." (PMID 41153666, 2025). "Furthermore, AR activation by its canonical pathway has been associated with the inhibition of the transforming growth factor-β pathway-induced antiproliferative and proapoptotic response in glioblastoma cells." (PMID 38233838, 2024). "For instance, a key consideration when selecting an AR antagonist for glioblastoma treatment is the ability of the drug to cross the blood–brain barrier." (PMID 41228208, 2025). "Enzalutamide, an AR inhibitor, decreases the density of cancer stem cell populations and improves survival in a glioblastoma orthotopic mouse model." (PMID 40358199, 2025). "AR expression in glioblastoma samples was assessed both at RNA (qRT-PCR) and protein levels (WB and immunofluorescence)." (PMID 38233838, 2024). "An in vitro study with glioblastoma cell lines reported AR activation that was mediated by EGFR signaling." (PMID 38233838, 2024). "Taken together our study and other pieces of evidence support the implication of the AR in glioblastoma pathogenesis mainly by its canonical pathway (i.e., androgen dependent)." (PMID 38233838, 2024). "For example, it has been uncovered that androgen receptor activity is correlated with poor prognosis in Glioblastoma." (PMID 38711550, 2024). "This study focused on analyzing the relationship between circulating androgen levels and AR activity with the clinical, molecular, and radiological features of glioblastoma." (PMID 38233838, 2024). "AR immunofluorescence (n = 16) was mainly located in the cytoplasm of glioblastoma cells, as well as the nucleus, which showed variable intensity among patients." (PMID 38233838, 2024). "Our study demonstrated the efficacy of androgen receptor antagonists in extending the lifespan of mice with intracranial human glioblastoma, suggesting a promising approach to enhance patient outcomes in the fight against this challenging disease." (PMID 38203506, 2023). "AR is overexpressed in 56% of glioblastoma multiforme (GBM) specimens and AR antagonists induced dose-dependent death in several GBM cell lines and significantly reduced tumor growth and prolonged the lifespan of mice implanted with human GBM." (PMID 37175938, 2023). "The findings of this study align with and extend the growing body of literature that highlights the pivotal role of androgen receptor (AR) antagonists in the treatment of glioblastoma." (PMID 38203506, 2023). "As an emerging therapeutic strategy, targeting the RTK/AR axis is one to be explored in greater depths before any conclusions can be drawn on its benefit in future glioblastoma clinical trials." (PMID 37857607, 2023).
glioblastoma (continued). "Motivated by these results, the current study aimed to ascertain the therapeutic potential of AR antagonists in intracranial models of human glioblastoma." (PMID 38203506, 2023). "This aligns with our pursuit of personalized therapy based on the level of AR expression within glioblastoma tumors, bringing us closer to tailoring treatments to individual patients." (PMID 38203506, 2023). "AR antagonists, including bicalutamide and enzalutamide, induce dose-dependent cell death in glioblastoma and glioblastoma-initiating cell lines (GIC)." (PMID 38203506, 2023). "A noteworthy development is the recognition of AR expression in a considerable percentage of glioblastoma cases, suggesting a promising avenue for potential therapeutic interventions." (PMID 38203506, 2023). "This exploration revealed a significant (p < 0.05) concentration-dependent induction of cell death in three glioblastoma cell lines and two glioma-initiating cell lines upon treatment with AR antagonists." (PMID 38203506, 2023). "In conclusion, our study contributes to the expanding body of literature supporting AR antagonists and innovative drug formulations as potential game-changers in glioblastoma treatment." (PMID 38203506, 2023). "We aimed to further investigate the efficacy of AR antagonists in intracranial models of human glioblastoma." (PMID 38203506, 2023). "Our unpublished data demonstrated the effects of testosterone on inducing AR mRNA and protein expressions in human and murine glioblastoma cells." (PMID 36013056, 2022). "Regarding the mechanisms, exposure of human glioblastoma cells to testosterone induced AR and PARD3B gene expressions and successively stimulated cell proliferation and colony formation." (PMID 36013056, 2022). "Compared to HA-h cells, levels of AR protein in human U87 MG and U87 MG-R glioblastoma cells were upregulated." (PMID 36235203, 2022). "Our unpublished data further demonstrated the effects of testosterone on inducing AR mRNA and protein levels in human drug-sensitive and -resistant glioblastoma cells." (PMID 36235203, 2022). "This study was designed to evaluate the effects of enzalutamide, a specific inhibitor of the AR, on killing drug-resistant and -sensitive glioblastoma cells and the possible mechanisms." (PMID 36235203, 2022). "The present study demonstrated a positive role of the testosterone AR signaling alliance in the proliferation of human glioblastoma cells." (PMID 36013056, 2022). "In the present study, we also showed the toxic effects of enzalutamide, an inhibitor of the AR, on killing human glioblastoma cells." (PMID 36235203, 2022). "Our data showed augmented expression of AR mRNA in human U87 MG and U87 MG-R glioblastoma cells compared to normal human astrocytes." (PMID 36235203, 2022). "Accordingly, this study demonstrated the de novo roles of the testosterone AR signaling axis in tumorigenesis of human glioblastomas through stimulating cell proliferation and colony formation." (PMID 36013056, 2022). "RNA analyses were carried out to determine the roles of the testosterone AR signaling axis in regulating PARD3B gene expression in human glioblastoma cells." (PMID 36013056, 2022). "Reducing AR activation by enzalutamide simultaneously inhibited testosterone-induced PARD3B mRNA expression in human glioblastoma cells." (PMID 36013056, 2022). "More importantly, lowering AR activity resulted in a significant attenuation of testosterone-induced proliferation and colony formation of human glioblastoma cells." (PMID 36013056, 2022). "Paoletti and cols found the expression of AR in 21.6% of 57 samples from 25 glioblastomas, 18 anaplastic astrocytomas, and 14 other types of astrocytomas." (PMID 33752729, 2021).